IL6 (interleukin 6)
Diseases named in the same sentence as IL6 in open-access papers (continued):
Sharing a sentence is not in itself a finding about the gene and the disease.
inflammation (continued). "To more closely mimic the pathophysiological conditions of FLS in an osteoarthritic joint, we employed IL-1β as an inflammation inducing agent that is pivotally involved in joint inflammation and cartilage destruction and induces excessive production of IL-6." (PMID 25312962, 2015). "We investigated the role of interleukin 6 (IL6) in inducing activation of ILCs in mice and in human beings with chronic intestinal inflammation." (PMID 25917784, 2015). "In adults and children with suppurative lung disease, airway inflammation is characterised by elevated levels of neutrophils, IL-1β, IL-6 and IL-8." (PMID 26066058, 2015). "Chronic inflammation, defined as average levels of serum interleukin-6 from 2 measures 5 years apart, was assessed in 1997-1999 and 2002-2004." (PMID 25305231, 2015). "Weaning induces transient gut inflammation in piglets and the expression levels of some pro-inflammatory cytokines such as IL-1β, IL-6 and TNF-α were up-regulated in newly weaned piglets." (PMID 24609095, 2014). "Our previous study of airway inflammation has demonstrated that the induction of IL-6 and CCL2 upon the interaction of basophils and bronchial epithelial cells under IL-17A stimulation was differentially regulated by ERK, JNK, p38 MAPK, and NF-κB pathways." (PMID 24782592, 2014). "Infiltrating leukocytes to areas of acute myocardial inflammation and post-MI myocardium are a source of inflammatory cytokines (e.g. IL-6, IL-1 and TNF-α) and contribute to local inflammation, remodelling and fibrosis of the myocardium." (PMID 23471223, 2013). "An increase in fat mass is associated with an increase in systemic inflammatory mediators which can exacerbate airway inflammation via inflammatory mediators such as leptin, adiponectin, Interleukin-6 (IL-6) and Tumour Necrosis Factor-alpha (TNF-α)." (PMID 23692648, 2013). "In lung tissue lysate, we found that KC and IL-6 concentrations were basally elevated consistent with the constitutive neutrophilic lung inflammation seen in Sphk1−/− mice." (PMID 22355325, 2012). "HIV-related chronic inflammation determines the expression of several cytokines especially in mononuclear cells such as IL-6, IL-8 and TNF α which activate endothelial cells and enhance leukocyte adhesion." (PMID 21612582, 2011). "We have previously shown that IL-6 administration prevents T/HS-induced liver and lung inflammation, in part by blocking NF-κB activation and reducing pro-inflammatory cytokine production." (PMID 21738667, 2011). "Moreover, airway transfer of Hyper-IL-6-conditioned DCs induced neutrophilic airway inflammation and Th17 polarization, while transfer of DCs conditioned with Hyper-IL-6 plus sgp130 markedly mitigated these responses." (PMID 41972168, 2026). "Chronic systemic inflammation, including C-reactive protein (CRP), interleukin-6 (IL-6), and tumor necrosis factor-alpha (TNF-α), has been associated with childhood maltreatment, and systemic inflammation has been identified as a gestational risk factor for adverse neurodevelopment in offspring." (PMID 40920854, 2025). "Emerging data from early-phase human studies indicate that standardized herbal extracts can reduce chronic systemic inflammation (evidenced by decreases in IL-6 and TNF-α), correct energy dysmetabolism, and simultaneously suppress proteolysis while promoting myofibrillar protein synthesis." (PMID 41514616, 2025). "Gene expression analysis in the ileum showed that OVX significantly induced intestinal inflammation, as evidenced by increased expression of pro-inflammatory cytokines (Tnf-a, Il-1b, Il-6, and Il-17) and reduced expression of the anti-inflammatory cytokines (Il-10 and Ifng)." (PMID 41466098, 2025). "Intestinal inflammation should stimulate macrophages/Th17 to secrete IL-6, which then activates the JAK-STAT3 pathway of B cell, thereby upregulating the Igκ enhancer expression (like Igkv16-104) and promoting antibody secretion, thereby exacerbating inflammation or tissue damage." (PMID 41373555, 2025).
inflammation (continued). "Research on rodents has shown that polystyrene microplastics (PS-MPs) can accumulate in reproductive tissues, leading to ovarian inflammation, reduced oocyte quality, and altered biomarker levels such as interleukin-6 (IL-6), glutathione (GSH), and mitochondrial dysfunction." (PMID 40427269, 2025). "However, while Il6 (interleukin-6) was unaltered, a reduced expression of Il1b (interleukin-1beta), a master pro-inflammatory cytokine in joint inflammation, was significantly reduced in the OA knees of Cxcl9-deficient mice 4 weeks after ACLT." (PMID 40047894, 2025). "Additionally, DAT attenuated I/R‐induced cardiac inflammation via the suppression of macrophage proinflammatory activities by suppressing IL‐6 production." (PMID 40089859, 2025). "Leukocyte counts, C-reactive protein (CRP), interleukin-6 (IL-6), interleukin-10, and tumor necrosis factor-α (TNF-α) are the markers used in most studies that are determined to be associated with low-grade chronic inflammation." (PMID 40332421, 2025). "Microglia activation results in chronic brain inflammation and an increase in proinflammatory cytokines such as TNF-α, IL-1β, and IL-6, which may be closely linked to the pathological features of HE." (PMID 39220284, 2024). "Our observations of IL-6 and IL-15 raise the question of whether treatment with anti-IL-6 or anti-IL-15 could be effective in a transition from musculoskeletal complaints to chronic joint inflammation." (PMID 38457608, 2024). "Decreased bone mass and bone density are caused by several factors involved in the pathogenesis of RA, such as the presence of pro-inflammatory cytokines (tumor necrosis factor-TNFα, Interleukin-1-IL-1, Interleukin-6-IL-6) and chronic systemic inflammation, which impacts bone metabolism." (PMID 38672734, 2024). "Notably, the intervention significantly reduces IL-6 levels, offering prospects for managing chronic inflammation and related diseases." (PMID 38525752, 2024). "Additionally, CBD-X significantly reduces pro-inflammatory cytokines IL-8 and IL-6 in neutrophils and impairs their migration, a critical step in airway inflammation." (PMID 39459021, 2024). "Several blood parameters, specifically blood serum IL-6, D-dimer, C-reactive protein, neutrophils, lymphocytes, monocytes, eosinophils, and basophils counts, were substantially higher than the normal ranges typical for acute viral inflammation." (PMID 37765004, 2023). "Transwell co-cultures of Caco-2 cells and U937-derived macrophages were used as models of LPS-induced intestinal inflammation to test the effect of ME-3 on release of the pro-inflammatory cytokines Tumor Necrosis Factor α, Interleukin-6, and Interleukin-8, was measured by ELISA." (PMID 37047193, 2023). "In practice, a rapid IL-6 or a rapid bedside MMP-8 test of amniotic fluid can be used for the rapid diagnosis of intra-amniotic inflammation and nanopore sequencing would allow the diagnosis of the causative microbe or, in the absence of microorganisms, sterile intra-amniotic inflammation." (PMID 36503654, 2023). "One explanation for these results could be related to different events involved in the pathogenesis ofCOVID-19: severe lung inflammation, triggered by IL-6, and the involvement of HE4 in the respiratory defense mechanisms promoted by innate immunity." (PMID 37297598, 2023). "It is also expected that curtailing the establishment of pancreatic inflammation by reducing the intra-pancreatic production of IL-6, CXCL1, and MCP-1, would lead to significantly reduced T-cell proliferation and chemotaxis, recruitment of neutrophils, and macrophages, respectively." (PMID 37180135, 2023). "IL-6 is involved in chronic autoimmune inflammation and can induce cytokine storm." (PMID 37649020, 2023). "The pathogenesis may be that PM and O3 can stimulate macrophages and epithelial cells in the airway to release various pro-inflammatory mediators (such as IL-1, IL-6 and IL-8), leading to lung inflammation, oxidative stress and lung injury." (PMID 37978503, 2023).
inflammation (continued). "For instance, the effect of butyrate to protect against gut inflammation has been proven to be dependent on the inhibition of HDACs in macrophages and dendritic cells to down-regulate pro-inflammatory cytokines, e.g., IL-1b, IL-6 and IL-8." (PMID 37110213, 2023). "However, since pY-STAT3 regulates inflammatory responses, both by blocking IFNγ induced STAT1 and IL-6 induced NFκB, inhibiting pYSTAT3 exacerbated cardiac inflammation." (PMID 36844399, 2023). "In vivo, treatment of Aspergillus-infected Il1r1–/– mice with anakinra increased the ratio of LC3-II/I and decreased p62, a ubiquitin-binding protein that is selectively degraded by autophagy; inhibited IL-6, IL-17A, IL-1β, and IL-1α production; increased IL-10; and ameliorated lung inflammation." (PMID 34847078, 2022). "IL-6 production is mainly operated via NF-kB transcription factor and its secretion in airway epithelia is induced by flagellin, a compound of bacterial flagellae, a strong mediator of pulmonary inflammation, and cognate TLR5 ligand." (PMID 36140341, 2022). "The expression levels of IL-6 can effectively reflect the severity of tissue and cell damage and can be used as the serological index for the clinical diagnosis of acute and chronic inflammation." (PMID 35531475, 2022). "Similar characteristics were unveiled in a mouse model, as Moraxella-infected mice showed augmented levels of IL-6, IL-1β, IL-17, and tumor necrosis factor α (TNF-α) in lungs, and neutralization of IL-17 and TNF-α was sufficient to accelerate airway inflammation and reduce the risk of AAD." (PMID 36060784, 2022). "For example, IL-6 is recognized as an inducer of retinal vascular inflammation and permeability." (PMID 35740425, 2022). "Measuring IL-6 levels in the serum or CSF in ICI-mediated CNS inflammation can help to determine patients that might benefit from therapeutic anti-IL-6 blockade." (PMID 35043373, 2022). "Activated IL-17 also activates epithelial cells, fibroblasts, and macrophages, releasing granulocyte-macrophage colony-stimulating factor (GM-CSF), TNF-α, PGE2, IL-1, IL-6, and IL-8, which are not only involved in airway remodeling but also promote further exacerbation of airway inflammation." (PMID 35815290, 2022). "IL-6 possesses both pro- and anti-inflammatory properties and is associated with the pathological significance in IBD development, thus, is observed as a distinguishable mediator of intestinal inflammation." (PMID 35120159, 2022). "Aging leads to increased levels of pro-inflammatory factors (especially CRP, TNF-α, and IL-6) in the blood, thereby inducing long-term chronic inflammation and decreased immune function, which is also a major factor for the increased chronic disease risk in the elderly." (PMID 36294194, 2022). "Inhalation of ambient air pollution consisting of various toxic substances may induce pulmonary inflammation, and an oxidative stress response and induce the prothrombotic state through β2AR, IL-6, and the TNF-α signaling pathway." (PMID 35886623, 2022). "Both IL-6 and IL-8 may mediate nasal inflammation in OSA patients, and were positively correlated with AHI." (PMID 33571266, 2021). "The increased amount of pro-inflammatory cytokines such as interleukin-1B (IL-1B), interleukin-6 (IL-6), interleukin-12 (IL-12) and interferon gamma (IFN-γ) in the serum was shown to be associated with pulmonary inflammation and extensive lung damage in SARS patients." (PMID 34834033, 2021). "However, it has been shown that IL-6-driven signaling restrains the recruitment of neutrophils in an animal model of acute peritoneal inflammation." (PMID 34040603, 2021). "In the current study, H. hepaticus infection in male BALB/c mice induced chronic hepatic inflammation throughout the process by stimulating the secretion of pro-inflammatory cytokines such as IL-6, Tnf-α, and Tgf-β, which resulted in the development of hepatic preneoplasia." (PMID 35046917, 2021).
inflammation (continued). "Thus, Ang II-AT1R signaling can create an IL-6-mediated positive feedback loop of NF-κB signaling, a mechanism known as the IL-6 amplifier, during lung inflammation followed by ARDS with multiorgan failure and coagulation." (PMID 33014208, 2020). "Biomarkers for vascular inflammation include a high plasma level of C-reactive protein, soluble cell-adhesion molecules, von Willebrand factor, aldosterone, and proinflammatory cytokines like interleukin-6 or tumor necrosis factor α." (PMID 32408603, 2020). "And as IL-6 activates gluconeogenesis and the hepatic secretion of triglycerides, its urinary secretion may reflect more than renal inflammation alone." (PMID 31886287, 2019). "There is striking evidence that IL-6 may be involved in hypoxia-induced lung inflammation and pulmonary vascular remodeling and is possibly responsible for the occurrence of high-altitude diseases." (PMID 30993032, 2019). "In several animal models of intestinal inflammation, the disease could be alleviated by specific blockade of IL-6 trans-signaling with sgp130Fc." (PMID 31694340, 2019). "In addition, IL-6 has been found to have a role in acute liver inflammation following Con A administration." (PMID 29643811, 2018). "Progression of HF was correlated with the accumulation of M1 macrophage phenotype in the myocardium and increased production of M1 macrophages, associated with production of proinflammatory cytokines such as IFNγ, IL-6, and TNFα, which all lead to cardiac inflammation." (PMID 30024944, 2018). "However, overwhelming activation of NF-kB leads to increased expression of inflammatory cytokines, such as IL-6, which contributes to the development of pancreatic inflammation." (PMID 28704954, 2017). "Because TNF, IL-6, and IL-13 are expressed by various leukocytes, we decided to investigate whether eosinophil-specific products could also drive chronic intestinal inflammation." (PMID 26200014, 2015). "Our preclinical data support the possibility that targeting IL6 may be therapeutically tractable in chronic gut inflammation." (PMID 25917784, 2015). "During another experiment, it was also demonstrated in mice lacking the gene for IL-6 that intra-articular injection of IL-6 reduces the loss of proteoglycans in the acute phase of chronic joint inflammation and induces the formation of osteophytes." (PMID 24876674, 2014). "Therefore, we measured cytokines (TNFα, IL-1β, IL-6) and a chemokine (KC) in whole lung homogenates as an additional readout for pulmonary inflammation." (PMID 24244609, 2013). "Thus, pharmacological inhibition of Stat3 using GQ-ODN in rats subjected to T/HS and resuscitated with IL-6 completely blocked IL-6-mediated Stat3 activation and IL-6-mediated prevention of liver inflammation." (PMID 21738667, 2011). "Although measurement of the levels of IL-23 protein is technically inconsistent, levels of IL-12(p40), one of two heteromers making up the IL-23 protein, were increased by E2, as were IL-6 and TNFα, also important early mediators of acute lung inflammation that induce IL-17." (PMID 21118573, 2010). "Previous studies have demonstrated that blocking IL-6 trans-signaling inhibits T lymphocyte polarization into the gamma-delta (γδ) T cell during airway inflammation, which could explain the increased number of unpolarized T cells observed in immune organs in our study." (PMID 40368371, 2025). "Indeed, in obese asthmatic subjects, a neutrophilic pattern of inflammation—both bronchial and systemic—has been previously demonstrated, suggesting the involvement of non-T2-type pathways such as adipocites-derived IL-6 in the pathogenesis of airway inflammation." (PMID 41153688, 2025). "As kidney inflammation can contribute to systemic inflammation through the release of inflammatory mediators, we found an elevated neutrophil-to-lymphocyte ratio in the Mdm2-cKO mice compared with the control group (P = 0.02) and a significant increase in plasma IL-6 protein levels." (PMID 39946208, 2025).